MTOR (mechanistic target of rapamycin kinase)
Diseases named in the same sentence as MTOR in open-access papers (continued):
Sharing a sentence is not in itself a finding about the gene and the disease.
cancer (continued). "Previous studies demonstrated that flavonoids exert anti-cancer effects through various pathways, as exemplified by apigenin inducing cell-cycle arrest and apoptosis of the cells, quercetin enhancing chemotherapy sensitivity by inhibiting the AGE/PI3K/AKT/mTOR pathway." (PMID 41006588, 2025). "Research shows that one of the main reasons is that the inhibition of mTOR alone may trigger the upstream loops, which may pave the way for the survival of cancer cells, hence not serving our purpose." (PMID 38584538, 2025). "Compared with FMN, the hybrid product could significantly inhibit the growth and migration of gastric cancer SGC7901 cells through the wnt/β-Catenin and AKT/mTOR pathways, and could be used as an inhibitor of SIRT1 to inhibit its expression, thereby inducing cancer cell death." (PMID 40098623, 2025). "Drugs based on well-known hormonal mechanisms involved in the pathogenesis of this cancer are still being actively developed, but more and more drugs are being implemented that target molecular targets related to carcinogenesis, such as the PI3K/AKT/mTOR pathway." (PMID 41157256, 2025). "Thus, there is an urgent need to develop advanced treatment strategies, such as combining traditional immunotherapies—like immune checkpoint inhibitors—with other anti-cancer treatments, including targeted therapies (e.g., TGF-β or PI3K/AKT/mTOR inhibitors) and chemotherapy." (PMID 40075635, 2025). "Jiang and Liu (2008) reported that the activation of the mTOR‐mediated HIF1 factor enhances several activities of endothelial and cancer cells, including the production of proteins, blood vessel development, the spread of cancer cells, emigration, division, and the death of cells." (PMID 40717210, 2025). "The IGF system in cancer should be examined in the context of the extra-cellular and intra-cellular signaling networks, particularly phosphatidylinositol 3-kinase (PI3K), protein kinase B (Akt/PKB), mammalian target of rapamycin (mTOR), and forkhead transcription factors (FOXO)." (PMID 40283465, 2025). "The interaction of GBMs with autophagy signaling pathways could affect key autophagy-regulating proteins, such as Beclin-1, LC3, mTOR, and AMPK (AMP-activated protein kinase), either enhancing or suppressing autophagy; thus, modulating the survival or death of cancer cells." (PMID 40429669, 2025). "Consequently, selective AKT inhibition may surpass mTOR inhibitors in the management of CRC and serves as a potential strategy to avert tumor recurrence by targeting cancer stem cells." (PMID 39456981, 2024). "HOTTIP downregulation enhances apoptosis in cancer cells by pro-apoptotic proteins overexpression, caspases activation, and inhibition of the phosphatidylinositol 3-kinase (PI3K)/Ak strain transforming (AKT)/mechanistic target of rapamycin Kinase (mTOR) signaling pathway." (PMID 38559560, 2024). "In conclusion, it is necessary to approach the diagnosis and treatment of cancer as a network that integrates multiple signaling pathways such as PI3K/Akt/c-Myc, the nuclear factor kappa B, and PI3K/AKT/mTOR, and to explore potential drug combinations that could regulate this signaling network." (PMID 39337387, 2024).
cancer (continued). "However, this study focused on low-dose MEK/ERK and PI3K/AKT/mTOR pathway inhibition, which induced pericyte differentiation and overall vascular remodeling, but not cancer cell–growth inhibition." (PMID 39286984, 2024). "The oncogenic activation of the PI3K/AKT/mTORC1 pathway can also inhibit ferroptosis in cancer cells through downstream SREBP1/scd1-mediated adipogenesis, so the combination of mTOR inhibitors and other ferroptosis inducers for cancer treatment may be an excellent therapeutic target." (PMID 38755125, 2024). "The PI3K/AKT/mTOR pathway is consistently activated in cSCC but not in its precursor, AK, suggesting that its dysregulation may be responsible for pre-cancer to cSCC transition." (PMID 39199674, 2024). "As new therapeutic options have emerged, the need to characterize mTOR activity in malignant tumors has increased, particularly in cancers with elevated mTORC2 activity, which may not respond to traditional mTOR inhibitors that only target mTORC1." (PMID 38339294, 2024). "However, the complex nature of the PI3K/Akt/mTOR pathway due to its multiple levels of feedback and crosstalk with other pathways has challenged the full effect of PI3K inhibitors in the treatment of cancer patients." (PMID 38542151, 2024). "Previous studies showed that miR-20b has a tumour suppressor function in cancers and regulates essential biological processes such as cell proliferation, apoptosis, autophagy and migration, exerting its effects through diverse signalling pathways, including PI3K/AKT/mTOR, STAT, TGF-beta and ERK." (PMID 38255241, 2024). "In addition, by inhibiting the activity of mammalian target of rapamycin (mTOR), which is a negative regulatory factor of autophagy, or by promoting the production of reactive oxygen species (ROS), MLN4924 can induce autophagy in cancer cells." (PMID 39062453, 2024). "In sum, it is not yet clear how to target mTOR for cancer therapy by regulating ROS levels." (PMID 38583115, 2024). "In another study, rapamycin, an mTOR inhibitor, affects the downstream inactivation of S6K1 and 4E-BP1 by inhibiting phosphorylation, which decreases protein synthesis and cell cycle arrest in the G1 phase and suppresses the growth of various cancer cell lines." (PMID 39519229, 2024). "The present non-clinical study shows that gedatolisib, a pan-PI3K/mTOR inhibitor, exerts greater anti-proliferative and cytotoxic effects than single-node PAM inhibitors such as everolimus in the EC, OC, and CC cancer cell lines, regardless of their PAM pathway mutational status." (PMID 39456616, 2024). "Its position in the PI3K/AKT/mTOR pathway has made it a potential therapeutic target, and mTOR inhibitors, such as rapamycin, have been used to treat a variety of conditions and various other non-cSCC cancers." (PMID 39199674, 2024). "The extract was able to inhibit cancer cell growth, induce mitochondrial damage, induce apoptosis, and arrest the cell cycle through various molecular pathways involving Bcl family genes, c-myc proto-oncogenes, CDK inhibitors, as well as ERK, mTOR, and NFκB pathways." (PMID 38794168, 2024). "Given the clear role of mTOR activation in the stimulation of ribosome biogenesis and protein synthesis, it is intriguingly to speculate that in this type of malignancy SIRT7 may sustain cancer cells growth by stimulating these functions." (PMID 38383727, 2024).
cancer (continued). "In the last decade, efforts to better understand the cancer biology of this challenging tumor have revealed recurrent alterations in foundational signaling pathways within cell biology, such as tyrosine receptor pathways, RAS/MAPK, JAK/STAT, PIK3/AKT/mTOR, WNT/β-catenin, and cell cycle regulation." (PMID 38473265, 2024). "It has been shown that the anti-cancer properties of propolis and related flavonoids can prevent VEGF-mediated angiogenesis in prostate cancer by downregulating VEGFR2 and inhibiting the PI3K/Akt/mTOR pathway, as well as downregulating NADPH oxidase 1 (NOX1) and HIF-1." (PMID 39519572, 2024). "In addition, the therapeutic mechanisms of TM and TMQ were related to the activation of transcriptional misregulation in the cancer pathway, inhibition of the cholinergic synapse pathway, the AMPK signaling pathway and the PI3K/Akt/mTOR signaling pathway, and inhibition of tumor cell proliferation." (PMID 39508039, 2024). "In addition to targeting PI3K/Akt in cancer, the signal transducer and activator of the transcription 3 (STAT3) pathway counterbalances PI3K/Akt/mTOR signalling via PTEN and promotes tumourigenic proliferation, invasion, migration, and angiogenesis in most cancers." (PMID 38785562, 2024). "However, it was clearly demonstrated that the senescent phenotype did not prevent the exit of cancer cells from dormancy if their mTOR signaling was downregulated." (PMID 38418814, 2024). "There is no doubt that the Akt/mTOR pathway plays a significant role in various types of cancer." (PMID 38817867, 2024). "Furthermore, mTOR inhibition disrupts the activity of hypoxic inducible factor (HIF-1α), a crucial transcriptional regulator that aids cells in adapting to hypoxia and contributes to cancer cell resistance in radiotherapy." (PMID 38612893, 2024). "Additionally, investigations into the effects of anthocyanins on cancer cell survival and the AMPK/mTOR pathway revealed that anthocyanins extracted from Meoru exerted growth inhibitory effects by regulating the mTOR or GSK3β/β-catenin pathway in HT-29 colon and Hep3B cells, respectively." (PMID 39335919, 2024). "The authors also showed that a member of the mammalian target of rapamycin (mTOR) C2 complex, RICTOR, can bind to PRICKLE1 and that PRICKLE1-MINK1-RICTOR complex integrity is essential for AKT (protein kinase B, PKB) activation, focal adhesion regulation, as well as migration of cancer cells." (PMID 39727954, 2024). "However, the PI3K/Akt/mTOR pathway is not the only translation regulatory mechanism dysregulated in cancer." (PMID 38476632, 2024). "Furthermore, CBD disrupts cancer cell proliferation by regulating cell cycle progression and interfering with the signalling pathways crucial for cell growth and survival, such as the PI3K/Akt/mTOR pathway." (PMID 38891847, 2024). "However, the relationship between HMGA1 and responses to mTOR inhibitors in cancer has not been reported." (PMID 38725843, 2024). "Chronic inflammation and cancer are mutually intertwined conditions, both driven by activation of common signaling pathways including signaling via nuclear factor kappa B (NF-kB), signal transducer and activator of transcription 3 (STAT3), and mammalian target of the rapamycin (mTOR)." (PMID 37020461, 2023). "Interestingly, the targeting of PI3K/mTOR signaling pathway by dactolisib decreased the UBE2C levels in all cancer cell lines, regardless of their different levels of PI3K activation." (PMID 37215954, 2023). "However, despite alterations in mRNA translation being a major mechanism modulating gene expression downstream of mTOR in cancer cells, translatome studies are lacking in TSC stem cell models." (PMID 37880800, 2023).
cancer (continued). "Previous studies of other cancers and our study have indicated that mTOR targeting may induce cytostatic effects rather than the effective eradication of tumor cells, suggesting the potential advantage of combining mTOR targeting with cytotoxic agents." (PMID 38203186, 2023). "Beyond the role of C15:0 as an mTOR inhibitor and AMPK activator, C15:0 supports healthy cellular signaling as a dual partial PPAR α/δ agonist, JAK-STAT inhibitor, and HDAC6 inhibitor, which are well-established moderators of metabolism, lipids, inflammation, and cancer." (PMID 37960259, 2023). "Research indicates that the impact of mTOR inhibitors on CSC may rely on the genetic background and rewiring of cancer stemness pathways; however, the connection between mTOR inhibitors and CSC is complicated, and their further relationship to RiBi or tumor cell resistance has not yet been reported." (PMID 38002277, 2023). "In addition, the level of prostaglandin is often elevated, and prostaglandin E2 is thought to inhibit apoptosis of cancer cells, and increase tumor invasion and angiogenesis through the NF-κB, MAPK/JNK/p38, and VEGF/PI3kinase/Akt/mTOR pathways and epigenetic modification." (PMID 37124724, 2023). "However, since mTOR is widely involved in various biological processes in most cells, mTOR inhibitors do not provide substantial benefits to patients with cancer." (PMID 38156109, 2023). "We also probed whether the requirement for mTOR is higher in cancer cells than in non-cancerous cells." (PMID 37298315, 2023). "However, the toxicity and adverse effects of these mTOR inhibitors make it difficult to treat cancer, which has significant negative effects on the patients." (PMID 37513916, 2023). "Therefore, we postulated that the regulation of 5-LO expression by PI3K/mTOR and MEK-1/ERK signaling is a mechanism that might apply to cancer cells from a solid origin in general." (PMID 36849252, 2023). "Furthermore, we show here that a number of cancer cell lines that do not express 5-LO under conventional cell culture readily up-regulate the enzyme upon inhibition of PI3K/mTOR and/or MEK-1/ERK signaling." (PMID 36849252, 2023). "All the in vitro and in silico findings of the present research work against anti-HepG-2 cancer cell line and four key enzymes EGFR, PI3K, mTOR, and Tubulin polymerization conclude that the 2,5-dimethoxy based bromobenzofuran-oxadiazole BF-5 could be the potential lead anti-HepG2 cancer agent." (PMID 36769327, 2023). "Future research focusing on the crosstalk between the PI3K/AKT/mTOR signaling axis and the cellular metabolism in HCC may help to reveal the impact of metabolic reprogramming in cancer cells and contribute to the development of novel potential therapeutic agents." (PMID 36768977, 2023). "However, this seems not to occur in bladder cell lines representing high-grade cancers, because mTOR levels on lysosomes do not increase." (PMID 36709383, 2023). "Importantly, Huh6 shared common cancer pathways involved in PI3K, mTOR and Hippo signaling." (PMID 37414763, 2023). "Amino acid transporters, including LAT1, can activate mTOR signals and various cancer-related molecules (HIF1A, growth factors, and kinases) through regulation of amino acid metabolism and protein synthesis, leading to cancer stemness and metastatic invasiveness, as well as therapeutic resistance." (PMID 36768934, 2023). "The crude Astragalus saponins extracted from Astragalus membranaceus (Fabaceae) exhibited anti-cancer effects against colon and gastric cancer at 80 and 50 μg/mL, respectively, via inhibiting angiogenesis-inducing signaling pathways, including VEGF, bFGF, HIF-1α, and PI3K/mTOR/Akt." (PMID 36984763, 2023).
cancer (continued). "In addition, the mTOR signaling pathway has been found to be upregulated in HCC tissues compared to the surrounding cirrhotic tissues and is involved in many cancer markers, including cell growth, metabolic reprogramming, proliferation, and inhibition of apoptosis." (PMID 37400770, 2023). "However, LAT1 and mTOR have been known to regulate cancer-related molecules not only tumor-side, but also host-side, acting on factors of the tumor microenvironment such as the extracellular matrix, stromal cells, endothelial cells, and immune cells." (PMID 36768934, 2023). "HIF‐1 signaling can be inhibited indirectly or indirectly; for example, PI3K/Akt/mTOR signaling pathway can control the expression of HIF‐1a, and by inhibiting this pathway, HIF‐1 α expression is downregulated, increasing MDR cells' sensitivity to cancer treatments." (PMID 37668041, 2023). "In addition, ST8SIA3 and GALNT9 might have an inhibitive role in cancer promotion by negatively modulating the activity of DNA damage and the EMT, PI3K/AKT, and mTOR pathways." (PMID 37663248, 2023). "In agreement with our results, a previous study demonstrated that the exposure of cancer cells to malignant PF samples induced epithelial-to-mesenchymal transition (EMT), which is an exacerbated stem cell phenotype, mainly through the activation of the PI3K/AKT/mTOR axis." (PMID 37762343, 2023). "In our vascular endothelial cells, the mTOR and PI3K-AKT signaling genes were hypermethylated at low FSS, suggesting that it might inhibit the pathway activations and the cell proliferation as well as the roles in cancer cells." (PMID 36743697, 2023). "Importantly, mTOR persistently restrains the tumor-suppressive function of 4E-BP1 via phosphorylation thereby releasing 4E‐BPs from eIF4E and enabling cap-dependent translation initiation in cancer." (PMID 37596643, 2023). "Additionally, PI3K inhibitors like Taselisib might also work for Her2 overexpression cancer cells, considering that HER2 induces the PI3K/AKT/mTOR pathway." (PMID 38203635, 2023). "PHF5A participates well in progression of different types of cancers including breast, lung, hepatocellular, lung adenocarcinoma and gastric tumors occurs through regulation/stimulation of numerous signaling pathways such as AKT/mTOR, NF- κB, IGF-1 and YAP signaling pathways." (PMID 37483794, 2023). "In addition to the AKT pathway, other signaling pathways have also been reported to be involved in PDIA3-mediated biological functions in cancers, such as STAT3 signaling, EGFR signaling, 1alpha, 25-dihydroxy vitamin D3 [1,25(OH)2D3]-mediated pathway and mTOR signaling." (PMID 38213579, 2023). "Here, we connect dysregulated signaling in the MAPK and PI3K/PDK1/AKT/mTOR (where PDK1, phosphoinositide-dependent protein kinase 1; mTOR, mammalian target of rapamycin) pathways with dysregulated cell cycle subverting normal cell proliferation and differentiation, resulting in NDDs or cancer." (PMID 37124926, 2023). "Notably, the expression of EREG in stromal cells is upregulated and activates several downstream signaling pathways, including the MAPK AKT/mTOR and JAK/STAT pathways, in cancer cells by paracrine signaling, promoting their malignant phenotype and accelerating the progression of cancer." (PMID 37077811, 2023). "In addition, lncRNAs may regulate the activity of signaling pathways involved in cancer pathogenesis, such as the Wnt/β-catenin, PI3K/Akt/mTOR, and MAPK/ERK pathways." (PMID 37232821, 2023). "Activation of the PI3K/AKT pathway promotes the mechanistic target of rapamycin (mTOR), effectors of which include hypoxia-inducible factor 1 (HIF-1), activator protein 1 (AP-1), and nuclear factor kappa B (NF-κB) that play an important role in promoting cancer." (PMID 37396849, 2023).